ACTN4 (actinin alpha 4)
Diseases named in the same sentence as ACTN4 in open-access papers (continued):
Sharing a sentence is not in itself a finding about the gene and the disease.
lung adenocarcinoma (6 papers, 2016 to 2024). A carcinoma that arises from the lung and is characterized by the presence of malignant glandular epithelial cells. "In studies related to lung adenocarcinoma, high expression of ACTN4 has been identified as a marker of platinum-based treatment outcomes in patients." (PMID 37626047, 2023). "In an in vitro study using cell lines of lung adenocarcinoma, a decrease of ACTN4 expression by siRNA reduced metastatic ability." (PMID 36139525, 2022). "High ACTN4 expression has been identified as a marker of the platinum-based therapy outcome in lung adenocarcinoma patients." (PMID 36476259, 2022). "In another study, ACTN4 protein expression was reported to be a promising biomarker in patients with completely resected stage II–IIIA lung adenocarcinoma." (PMID 36139525, 2022). "Amplification of ACTN4 was also found to correlate with the survival outcomes of lung adenocarcinoma patients." (PMID 31766144, 2019). "The A549 cell line, which is an NSCLC cell line that was derived from patients with lung adenocarcinoma, has gene amplification of ACTN4." (PMID 27121206, 2016). "Our retrospective data suggested that patients in the subgroup of ACTN4 (+) with stage-I lung adenocarcinoma who underwent ADJ with tegafur-uracil displayed improved overall survival (data not shown)." (PMID 27121206, 2016). "Moreover, recent studies have suggested the usefulness of ACTN4 for the evaluation of patients with early-stage lung adenocarcinoma." (PMID 36139525, 2022). "According to recent studies, overexpression of the ACTN4 gene may be a positive marker for the application of platinum-based therapy in lung adenocarcinoma patients." (PMID 36476259, 2022). "Evaluation of ACTN4 may be beneficial in patients with lung adenocarcinoma as well as those with lung squamous cell carcinoma." (PMID 36139525, 2022). "In addition to its potential as a prognostic factor, ACTN4 gene amplification may also be a predictive biomarker for adjuvant UFT therapy in patients with completely resected stage I lung adenocarcinoma." (PMID 36139525, 2022). "Moreover, in another study, using immunohistochemical analysis (IHC) we recently retrospectively demonstrated that stage-II/IIIA patients with lung adenocarcinoma in which the ACTN4 protein is overexpressed got clinical benefit for overall survival from ADJ with cisplatin and vinorelbin." (PMID 27121206, 2016). "Our previous study demonstrated that gene amplification of ACTN4 was significant prognostic biomarker for the stage-I patients with lung adenocarcinoma who never underwent adjuvant chemotherapy." (PMID 27121206, 2016). "Comparative RNA-sequencing analysis of samples from the primary tumor, local lymph nodes and brain metastases from a single lung adenocarcinoma patient revealed high expression levels of ACTN4 in brain metastatic tissue but not in the lymph nodes, primary tumor, or normal lung tissues." (PMID 31766144, 2019). "Moreover gene amplification of ACTN4 is a prognostic biomarker for stage-I lung adenocarcinoma patients who never underwent ADJ after surgery." (PMID 27121206, 2016). "Although ACTN4 expression level did not correlate with the chemosensitivity of cancer cell lines for cytotoxic drugs, the metastatic potential of A549 lung adenocarcinoma cells was significantly reduced by ACTN4 shRNA in in vitro assays and in an animal transplantation model." (PMID 27121206, 2016). "Moreover, although we previously showed that gene amplification of ACTN4 is a prognostic biomarker of stage-I lung adenocarcinoma, in the present study we could not confirm the status of the copy number of ACTN4 from this database." (PMID 27121206, 2016).
cardiomyopathy (5 papers, 2015 to 2025). A disease of the heart muscle or myocardium proper. "We report a case of adolescent-onset FSGS with ACTN4 mutation diagnosed during ACEi therapy for the prevention of DMD-associated cardiomyopathy." (PMID 41013435, 2025). "Sepsis-induced cardiomyopathy in blood mononuclear cells and cardiac tissue cells is stimulated by serum levels of biomarkers (hsa-miR-23a-3p, hsa-miR-317, and hsa-miR-23b-3), which alter neurovascular-related HDAC7/ACTN4 signaling pathways linked to the NF-κB pathway." (PMID 35756932, 2022). "Some DEGs related to cytoskeleton organization (e.g. MTSS1, ACTN4 and CALD1), cardiomyopathy (e.g. ITGB5) and immune response (e.g. C1S and C1R), as well as some regulators (e.g. LEF1 and hsa-miR-33a) might play pivotal roles in the progression of DN." (PMID 27613243, 2016).
glioblastoma (5 papers, 2009 to 2023). The most malignant astrocytic tumor (WHO grade IV). "It has been shown to form a complex with lncRNA SChLAP1 to regulate glioblastoma by activating NF-κB signaling and stabilizing ACTN4." (PMID 35549989, 2022). "ACTN4 has been shown to be degraded through the ubiquitin-proteasome pathway and can be stabilized in human glioblastoma." (PMID 34380780, 2021). "In addition, ACTN4 can be degraded through the ubiquitin-proteosome pathway and be stabilized in human glioblastoma cells." (PMID 34380780, 2021). "We identified the following five proteins that were present in all samples, both glioblastoma-derived EVs and HPA-derived EVs: THBS1, FN1, TGFBI, ACTN4, and LGALS3BP." (PMID 35454889, 2022).
non-small cell lung carcinoma (5 papers, 2015 to 2022). A group of at least three distinct histological types of lung cancer, including non-small cell squamous cell carcinoma, adenocarcinoma, and large cell carcinoma. "Curiously, no change in cisplatin resistance has been observed in the A549 non-small cell lung cancer (NSCLC) line after the ACTN4 gene knock-down." (PMID 36476259, 2022). "Analysis of patient information from the public database showed significant benefits of adjuvant chemotherapy against non-small cell lung cancers (NSCLC) expressing ACTN4 mRNA." (PMID 31766144, 2019). "In addition, ACTN4 was found to be highly expressed in a poor survival group of patients with non-small cell lung cancer, suggesting that ACTN4 is a significant prognostic predictor in this cohort of patients." (PMID 25885339, 2015). "For example, the knockdown of ACTN4 expression in ovarian carcinoma cell line DOV13, non-small-cell lung carcinoma A549, bladder cancer cells T24, J82, and KU19-19, leads to a reduction in both invasiveness and migration." (PMID 31766144, 2019).
colon cancer (4 papers, 2015 to 2024). "Our finding that ACTN1 and ACTN4 show differential affinities for ZYX may provide the molecular mechanism underlying the phenotypic outcome of ACTN overexpression in colon cancer cells." (PMID 25860875, 2015). "We first quantified the relative expression levels of endogenous ACTN1 and ACTN4 proteins in several colon cancer cell lines using purified recombinant proteins as external controls." (PMID 25860875, 2015). "The results from both DLD-1 cells and SW480 cells indicate that the biased expression of ACTN isoforms dictates the invasive property of colon cancer cells; higher relative expression of ACTN4 over ACTN1 tends to favor invasive phenotypes." (PMID 25860875, 2015). "This reduction in DBN1S142p resulted in increased binding of ACTN4 to F-actin, thereby stabilizing F-actin and ultimately leading to reduced MMP2 expression and inhibition of colon cancer cell migration." (PMID 39052867, 2024). "This, in turn, enhances the binding of ACTN4 to F-actin and stabilizes F-actin, ultimately resulting in reduced MMP2 expression and decreased migratory ability in colon cancer cells." (PMID 39052867, 2024). "Thus, elevation of ACTN4 protein expression and ancillary ZYX inhibition in colon cancer cells provides another mechanistic basis for cancer progression, while underscoring the importance of focal adhesion regulation in colon cancer." (PMID 25860875, 2015).
gastric cancer (4 papers, 2018 to 2022). A primary or metastatic malignant neoplasm involving the stomach. "ACTN4 can reduce cell adhesion and enhance the migration and invasion of gastric cancer cells, hence serving as a new therapeutic target for gastric cancer." (PMID 32670437, 2020). "The knockdown of ACTN4 in gastric cancer cells obviously increased cell-matrix adhesion and reduced gastric cancer cell migration and invasion." (PMID 32670437, 2020). "NF-κB was downregulated after the knockdown of ACTN4 in gastric cancer cells." (PMID 32670437, 2020).
Nephropathy (4 papers, 2022 to 2025). A nonspecific term referring to disease or damage of the kidneys. "This case report aims to offer a new perspective on DDS with novel WT1 and ACTN4 co-mutations, providing insight into the progression of nephropathy." (PMID 40890712, 2025). "In our published studies, we also confirmed that ANGPTL3 can affect the expression levels of podocyte lipid raft-associated molecules such as nephrin and ACTN4 in an adriamycin-induced nephropathy model and can then aggravate the cytoskeleton rearrangement and cell motility of podocytes." (PMID 36123608, 2022). "Genetic analysis revealed two mutations that were likely associated with the patient’s nephropathy: a WT1 variant, c.388_389insAC (p.Pro130Hisfs*34), and an ACTN4 variant, c.2698T > A (p.Ser900Thr)." (PMID 40890712, 2025).
osteosarcoma (4 papers, 2018 to 2020). A usually aggressive malignant bone-forming mesenchymal neoplasm, predominantly affecting adolescents and young adults. "These authors revealed that the decrease of ACTN4 expression by specific shRNA attenuated the level of phosphorylation of the RelA/p65 subunit of NF-kappaB in osteosarcoma cells." (PMID 31766144, 2019). "ACTN4 promotes migration and metastasis of osteosarcoma through the NF-κB Pathway48." (PMID 33033380, 2020). "Alpha-actinin-4 (ACTN4) is associated with different types of tumors, but its role in osteosarcoma (OS) is not known." (PMID 30879239, 2020). "In contrast, interaction with ACTN4 of the MDM2 binding protein (MTBP) abrogated ACTN4-mediated rearrangements of the actin cytoskeleton, thereby reducing the migratory activity of SaOs2-LM7 and U2OS osteosarcoma cells." (PMID 31766144, 2019).
astrocytoma (3 papers, 2010 to 2020). "During the occurrence and development of astrocytoma, ACTN1 and ACTN4 are regulated differently, and their effects on the malignant development of astrocytoma cells are opposite." (PMID 32670437, 2020). "However, it also has been shown that ACTN1 and ACTN4 contribute to distinct malignant properties of astrocytoma cells and that ACTN4 may be more important for cell motility and cell adhesion in some cell lines." (PMID 25885339, 2015).
atrial fibrillation (3 papers, 2019 to 2025). A disorder characterized by an electrocardiographic finding of a supraventricular arrhythmia characterized by the replacement of consistent P waves by rapid oscillations or fibrillatory waves that vary in size, shape and timing and are accompanied by an irregular ventricular response. "ACTN4/CAPN12 has been linked to CAD and the pathophysiology of atrial fibrillation." (PMID 38601677, 2024). "Notably, the ACTN4/CAPN12 locus associated with TortV is also associated with coronary artery disease, heart rate, and atrial fibrillation." (PMID 31597446, 2019).
salivary gland carcinoma (3 papers, 2014 to 2020). A carcinoma that arises from the major or minor salivary glands. "Multivariate analysis also revealed that vascular invasion and CNI of ACTN4 were independent risk factors for both salivary gland carcinomas including and excluding ADCC." (PMID 24574362, 2014). "We then investigated the correlation between protein expression levels and copy number of ACTN4 in salivary gland carcinomas excluding ADCCs." (PMID 24574362, 2014). "To remove the bias of the unique prognosis of ADCC, we also investigated the prognostic significance with CNI of ACTN4 in 37 salivary gland carcinoma patients excluding ADCC." (PMID 24574362, 2014). "Kaplan–Meier analysis revealed that CNI of ACTN4 was significantly correlated with poor outcome in overall survival of the 58 patients with salivary gland carcinoma, including ADCC (P = 0.0005, log-rank test)." (PMID 24574362, 2014). "This is the first report to examine the clinical usage of CNI of ACTN4 as a prognostic factor in salivary gland carcinoma." (PMID 24574362, 2014). "Univariate analysis revealed that vascular invasion (HR: 8.58; 95% CI: 2.16–34.11) and CNI of ACTN4 (HR: 4.18; 95% CI: 1.29–13.53) were significant positive predictors for death in salivary gland carcinomas excluding ADCC." (PMID 24574362, 2014). "The average copy numbers of ACTN4 in salivary gland carcinomas excluding ADCC were 5.12, 2.90, and 2.47 in tumors with strong expression (+3), moderate expression (+2), and negative staining (0 and +1), respectively." (PMID 24574362, 2014). "The present study is the first report that CNI of ACTN4, including gene amplification and high polysomy of ACTN4, was significantly correlated to histological grade and vascular invasion in salivary gland carcinoma." (PMID 24574362, 2014). "In the present study, we investigated the copy number of ACTN4 in salivary gland carcinomas by using fluorescent in situ hybridization (FISH)." (PMID 24574362, 2014). "CNI of ACTN4 was recognized in 14 of 58 patients (24.1%) with salivary gland carcinoma." (PMID 24574362, 2014). "We determined the copy number of ACTN4 in salivary gland carcinomas by using FISH." (PMID 24574362, 2014). "Copy numbers of ACTN4 were significantly increased in tumors with strong expression (+3) of actinin-4 in comparison with negative staining (0 and +1) and moderate expression (+2) (P < 0.01) in salivary gland carcinomas, excluding ADCC." (PMID 24574362, 2014). "Thus, CNI of ACTN4 is a novel indicator for an unfavorable outcome in patients with salivary gland carcinoma." (PMID 24574362, 2014). "Genetic alterations of 19q13.1 and ACTN4 have not yet been reported in salivary gland carcinoma." (PMID 24574362, 2014).
small cell lung carcinoma (3 papers, 2015 to 2020). Small cell lung cancer (SCLC) is a highly aggressive malignant neoplasm, accounting for 10-15% of lung cancer cases, characterized byrapid growth, and early metastasis. "Notably, a specific splice variant of ACTN4 mRNA with an alternative exon 8 was detected in small-cell lung cancer (SCLC)." (PMID 31766144, 2019).
bacterial meningitis (2 papers, 2018 to 2023). Inflammation of the membranes surrounding the brain and spinal cord due to a bacterial infection. "Transactivated EGFR recruitment of ACTN4, therefore, is likely to be a common mechanism utilized by multiple CNS-infecting bacterial pathogens for BBB penetration, and these molecules are potential targets for future prevention and therapy of bacterial meningitis." (PMID 30687645, 2018).
congenital nephrosis (2 papers, 2016 to 2024). "In contrast, mice deficient in ACTN4 do not have congenital nephrosis, suggesting that alterations in ACTN4 lead to podocyte damage and the development of FSGS by causing subtle cytoskeletal changes." (PMID 39446130, 2024).
COVID-19 (2 papers, 2022 to 2025). A disease caused by infection with severe acute respiratory syndrome coronavirus 2. "The respective APNet bipartite graph contained a large cluster (IL10RA, ACTN4, ITGB2, IL2RB, BIRC2, ITGAM, HMOX1, TIMP1) linked with established COVID-19 inflammatory and immune signalling cascades." (PMID 39921901, 2025). "Specifically, within upregulated, CAZA1, CO4A, ANXA4, and immunoglobulin kappa variable 3–20 (IGKV3-20) were significantly increased in mild disease COVID-19 while ACTN4 and fibrinogen beta (FGB) chain were significantly increased in severe COVID-19 individuals." (PMID 35760827, 2022). "Within the salivary proteins that were significantly increased in patients with COVID-19, five contributed most on the model: CAZA1, ACTN4, TGM3, CO4A, and ANXA4." (PMID 35760827, 2022).
diabetic nephropathy (2 papers, 2013 to 2021). "Expression of α-actinin-4 is decreased in a model of diabetic nephropathy as well as in FSGS caused by the ACTN4 K255E mutation." (PMID 33922367, 2021).
endometrial cancer (2 papers, 2023 to 2025). Primary or metastatic malignant neoplasm involving the endometrium (mucous membrane that lines the endometrial cavity). "Utilizing immunohistochemical staining (IHC) and fluorescence in situ hybridization (FISH), we meticulously evaluated actinin‐4 protein expression and ACTN4 gene amplification, respectively, within a large cohort of endometrial carcinoma patients." (PMID 41218617, 2025). "This could involve in vitro studies using endometrial cancer cell lines to investigate the effects of ACTN4 knockdown or pharmacological inhibition on key cancer‐related processes such as cell proliferation, migration, and invasion." (PMID 41218617, 2025).
hyperlipidemia (2 papers, 2022 to 2024). "ANGPTL3 could play a role in the mechanism of hyperlipidemia-associated podocyte injury via ACTN4." (PMID 36123608, 2022). "ACTN4 is a potential signaling molecule for ANGPTL3 in the mechanism of hyperlipidemia-related kidney injury." (PMID 36123608, 2022). "In summary, our study suggests that ANGPTL3 may participate in renal injury in hyperlipidemia and that ACTN4 is its target molecule in this mechanism." (PMID 36123608, 2022). "The IHC data primarily revealed that the ACTN4 staining intensity was weakened in hyperlipidemia-related glomeruli with prolonged high-fat diet feeding, suggesting that ACTN4 may be involved in podocyte injury caused by hyperlipidemia." (PMID 36123608, 2022). "ANGPTL3 can play a role through ACTN4 in a hyperlipidemia-related kidney injury model has not been reported." (PMID 36123608, 2022).
intrahepatic cholangiocarcinoma (2 papers, 2021 to 2023). A carcinoma that arises from the intrahepatic bile duct epithelium in any site of the intrahepatic biliary tree. "So, due to its regulation of Gdf9 expression in oocytes, CPEB3 is crucial for the growth of ovarian follicles and female fertility. hsa_circ_0050898, which was derived from the ACTN4 gene’s exons 1 to exons 20, was overexpressed in intrahepatic cholangiocarcinoma." (PMID 36827016, 2023). "Circ-ACTN4 binds YBX1 and stimulates FZD7 transcription, which in turn promotes intrahepatic cholangiocarcinoma (ICC) proliferation and metastasis, leading to malignant tumor growth and metastasis." (PMID 35116058, 2021).
large cell neuroendocrine carcinoma (2 papers, 2015 to 2019). A usually aggressive carcinoma composed of large malignant cells which display neuroendocrine characteristics. "In another study, this variant of ACTN4 protein was predominantly observed in high grade neuroendocrine lung tumors, including 60% of SCLC and 51% of large cell neuroendocrine carcinomas (LCNEC)." (PMID 31766144, 2019). "We established a specific antibody against ACTN4-SpEx8 and observed protein expression in SCLC and large cell neuroendocrine carcinoma (LCNEC) with immunohistochemistry among pathological samples of adenocarcinoma, squamous cell carcinoma, LCNEC, carcinoid, and SCLC." (PMID 26288717, 2015).
lymphoma (2 papers, 2018 to 2020). A malignant (clonal) proliferation of B- lymphocytes or T- lymphocytes which involves the lymph nodes, bone marrow and/or extranodal sites. "The selected genes included 36 genes mutated in at least one of the six OAML studied by WGS and/or at least in two of the eight lymphomas studied by WES, as well as two additional genes (CXCR4, ACTN4)." (PMID 32316399, 2020).